JAK1 (Janus kinase 1)
Diseases named in the same sentence as JAK1 in open-access papers (continued):
Sharing a sentence is not in itself a finding about the gene and the disease.
breast cancer (continued). "In conclusion, C6 ceramide inhibits canine mammary cancer growth and metastasis by targeting EGR3 through the regulation of the JAK1/STAT3 signaling pathway." (PMID 38338065, 2024). "To date, two IL-6Rα monoclonal antibodies (mAbs), a JAK1/2 inhibitor, and a small-molecule STAT3 inhibitor are being clinically investigated for breast cancer." (PMID 39768178, 2024). "STAT5 is also involved in breast tumorigenesis and Janus kinase 1 (JAK1) activation via the prolactin receptor, whereas JAK2 activity has been shown to enhance STAT5 signaling in breast cancer cells." (PMID 38339245, 2024). "Tissue microarrays consisting of breast cancer specimens from a retrospective cohort (n = 850) were stained for IL6R, JAK1, JAK2 and STAT3 via immunohistochemistry." (PMID 37199043, 2023). "Additionally, our own database analysis and several published reports have demonstrated high JAK1 amounts and activity in tumors, rendering JAK1 as a promising biomarker that correlates with clinicopathological characteristics within specific cancer types, for example, in breast cancer." (PMID 38201452, 2023). "Studies in the literature have focused on mRNA expression of JAK1 and JAK2 and have concluded high expression predicts better outcome in breast cancer." (PMID 37199043, 2023). "For example, there is a positive correlation between JAK1 and the infiltration of immune cells, such as CD8+ T cells and dendritic cells in breast cancer." (PMID 35928884, 2022). "In conclusion, we show here for the first time that DOR triggered migration and metastasis of breast cancer cells, which acts via oncogenic JAK1/2-STAT3 signaling and potentially promotes breast cancer progression through increased EMT." (PMID 33465556, 2021). "TRβ-driven tumor suppressive transcriptomic signatures include repression of known drivers of proliferation such as PI3K/Akt pathway, activation of novel signaling such as JAK1/STAT1, and metabolic reprogramming in both thyroid and breast cancers." (PMID 34503062, 2021). "Ruxolitinib, an FDA approved JAK1/2 inhibitor was found to attenuate STAT3 phosphorylation and reduce tumor growth in tamoxifen resistant breast cancer cells and is currently under clinical investigation (NCT02876302, NCT02066532, NCT03012230)." (PMID 33266219, 2020). "Recently, JAK1/STAT3 signaling was shown to be essential in breast metastasis, where STAT3 was identified as the crucial mediator of breast cancer migration upon upstream JAK activation." (PMID 33266219, 2020). "ODZ10117 did not significantly inhibit the JAK family of tyrosine kinases, including JAK1, JAK2, JAK3, and TYK2, in breast cancer cells and Hodgkin’s lymphoma cells." (PMID 31684051, 2019). "JAK1 was inversely correlated with tumor size status, lymph node status, and TNM of breast cancer patients." (PMID 31790361, 2019). "The expression of JAK1 was inversely correlated with tumor size status (P = 0.010), lymph node status (P = 0.001), and TNM staging (P = 0.001) of breast cancer patients." (PMID 31790361, 2019). "JAK1 mRNA levels were inversely correlated with the tumor size status, lymph node status, and TNM staging of breast cancer patients." (PMID 31790361, 2019). "Knock down of both JAK1 and JAK2 enhanced the lethality of lapatinib and of afatinib in the BT474 and SUM149 mammary carcinoma cells." (PMID 27379204, 2016). "This compound has also been shown to reduce the phosphorylation levels of Src, JAK1, and STAT-3 in MDA-MB-468 human breast cancer cells." (PMID 22554053, 2012). "Irrespective of their HER2 status, the breast cancer cell lines showed higher vulnerability to the inhibition of JAK1 (Janus Kinase 1) than the leukemia cell lines." (PMID 35994503, 2022). "In addition, correlation analysis from bc-GenExMiner v4.5 revealed that the expression of HDAC2, as well as JAK1, JAK2, and STAT1, was significantly correlated with that of PD-L1 in breast cancer." (PMID 34365463, 2021).
breast cancer (continued). "In a proof-of-principle experiment, we conditionally deleted the JAK1 tyrosine kinase in KRAS-transformed mammary cancer cells using the dual recombinase approach and found that lack of JAK1 was sufficient to block the constitutive activation of STAT3." (PMID 34675248, 2021). "Many cytokine and growth factor receptors trigger JAK1/2-STAT3/5 activation, however, it was somewhat unexpected and striking that a GPCR such as DOR could also activate STAT3 in breast cancer cells to a similar extent as IL-6 cytokine stimulation." (PMID 33465556, 2021). "Notably, we utilized pharmacologic inhibition of JAK1/2 and stable genetic STAT3 knockdown to conclude that opioid-triggered STAT3 activation promotes breast cancer migration and metastasis." (PMID 33465556, 2021). "Since the tumor purity in HER2+ breast cancer was not significant (P = 2.08e-02), the correlations between JAK1 expression and the 6 types of infiltrating immune cells needs further study to confirm these results." (PMID 31790361, 2019). "Moreover, down-regulation of JAK1/STAT3 phosphorylation confirms that these factors are critically involved in LDR-attenuated EMT and stemness in breast cancer cells." (PMID 28240233, 2017). "Together, EGFRvIII overexpression might decrease the sensitivity of breast cancer cells to trastuzumab via constitutively activating EGFR downstream signals including ERK, AKT, and Jak1/STAT3." (PMID 26474285, 2015). "Our study indicated that EGFRvIII expression could decrease the sensitivity of breast cancer cells against trastuzumab via activating the ERK, AKT and Jak1/STAT3 pathways, which suggested that EGFRvIII inhibitor might reduce trastuzumab resistance." (PMID 26474285, 2015). "Importantly, all nine PRL-induced transcripts were also partially suppressed by Jak1 knockdown, consistent with a significant role for Jak1 recruitment by PRL in breast cancer cells to maximize downstream signals." (PMID 23758962, 2013). "Future studies to identify the mechanism of activation of Jak1 by PRL receptors in breast cancer and the effect of Jak1-activation on PRL-modulated biology of breast cancer are now warranted." (PMID 23758962, 2013). "In a non-hematopoietic myoblast-like cell line, EPO has been previously reported to induce the tyrosine phosphorylation of JAK1, however, rEPO did not induce the tyrosine phosphorylation of JAK1 in mammary carcinoma cells." (PMID 17579721, 2007). "Ruxolitinib is a potent JAK1/2 inhibitor that was first approved for the treatment of myeloproliferative neoplasia (MPN) by the United States Food and Drug Administration (FDA) in 2011 and was subsequently used to investigate its anticancer effect in various solid tumors, including breast cancer." (PMID 35269680, 2022). "JAK1 is essential for IL-6-class inflammatory cytokine signaling, plays a critical role in metastatic cancer progression, and mediates the persistent oncogenic activation of STAT3 in mammary cancer cells that are driven by ERBB2 receptor tyrosine kinase signaling." (PMID 31790361, 2019). "This is also in line with the finding that the activation state of the tyrosine kinases JAK1, JAK2, and c-Src, which are considered to be responsible for phosphorylation of STAT3 Tyr705, was not significantly inhibited by the presence of 10 or 20 mM STATTIC in breast cancer cells." (PMID 30283459, 2018). "According to the efficacy of CH12 and the inhibition effect against ERK, AKT and Jak1/STAT3 pathway in EGFRvIII+HER2+ breast cancers, we wondered whether the combination of trastuzumab with CH12 could reverse trastuzumab resistance in EGFRvIII+HER2+ breast cancer." (PMID 26474285, 2015). "To test whether GH signaling in human T47D breast cancer cells, which express low levels of GHR and high levels of PrlR, is affected by extracellular acidosis, we assessed GH induction of phosphorylation of Jak2, Jak1 and Stat5 across a range of zinc ion concentrations at pHe 7.4 and 6.8." (PMID 24004716, 2013).
breast cancer (continued). "In contrast, Hodgkin's lymphoma HLDM-2 cells, breast cancer MDA-MB-468 cells and prostate cancer DU145 cells exhibited high levels of phospho-JAK1 and -JAK2 but not phospho-JAK3." (PMID 20149240, 2010). "JAK1 expression levels had significant positive correlations with infiltrating levels of CD8+ T cells, CD4+ T cells, macrophages, neutrophils, and dendritic cells in breast cancer and not with other B cells." (PMID 31790361, 2019).
atopic dermatitis (76 papers, 2016 to 2026). "Signal strength of positive infection and infestation-related adverse events associated with JAK-1 inhibitors in atopic dermatitis." (PMID 41255603, 2025). "Oclacitinib, while effectively managing itching and inflammation in dogs with allergic dermatitis through targeting the JAK1 pathway and inhibiting cytokines associated with inflammation, may also inadvertently alter the delicate balance of immune regulation." (PMID 40084163, 2025). "The patient, a veterinarian, had been self-administering oclacitinib (16–64 mg/day), a selective JAK1 inhibitor approved for the treatment of atopic dermatitis in dogs, daily for approximately 2 years to manage atopic dermatitis." (PMID 41503450, 2026). "Oclacitinib is a selective JAK1 inhibitor approved for the treatment of atopic dermatitis in dogs aged 12 months or older." (PMID 41503450, 2026). "Clinical characteristics of infections and infestations related to JAK-1 inhibitors in atopic dermatitis treatment (Q3 201–Q1 2025)." (PMID 41255603, 2025). "Molecular targeted therapies, including advanced atopic dermatitis (AD) treatment with Janus kinase 1 inhibitors (JAK1i) and anti-interleukin-13 antibodies (IL-13Ab), are emerging as effective options." (PMID 40861471, 2025). "Upadacitinib, a selective Janus kinase 1 (JAK1) inhibitor approved for atopic dermatitis and psoriatic arthritis, has shown potential benefits in PPP through several case reports." (PMID 40429269, 2025). "Gene expression, signal transduction, atopic dermatitis, and JAK1-selective inhibitors have emerged as prominent research areas in recent years, exhibiting significant potential for development." (PMID 40746612, 2025). "Upadacitinib is a selective oral JAK1 inhibitor approved for a variety of conditions including atopic dermatitis and psoriatic arthritis." (PMID 40034551, 2025). "Recent research has further highlighted the potential role of upadacitinib, a selective JAK-1 inhibitor, in the management of patients with concomitant atopic dermatitis (AD) and alopecia areata (AA)." (PMID 40075768, 2025). "Abrocitinib is a highly selective JAK1 inhibitor that has been approved for the treatment of moderate to severe atopic dermatitis (abbreviated as AD)." (PMID 40292287, 2025). "Baricitinib, a selective JAK1/2 inhibitor, is approved for active RA, alopecia areata (AA), and atopic dermatitis (AD)." (PMID 40305472, 2025). "IL-4 and IL-13 are closely related to atopic dermatitis, and they activate the intracellular JAK1/STAT6 pathway." (PMID 39599592, 2024). "Povorcitinib as a JAK1 inhibitor is also attempting to transfer the success of JAK inhibitors from atopic dermatitis to bronchial asthma in a phase II trial." (PMID 39600395, 2024). "Due to the diverse functions of JAK family members in various tissues and cell types, JAK1-selective inhibitors were developed and are used for the treatment of atopic dermatitis but remain under clinical evaluation for the treatment of asthma." (PMID 38880827, 2024). "There have been no reports of vitiligo being treated with oral Abrocitinib, a selective Janus Kinase 1 inhibitor approved for the treatment of moderate to severe atopic dermatitis." (PMID 38362228, 2024). "Abrocitinib, an oral JAK1 inhibitor, that curtails the signaling of IL-4 and IL-13, has been reported to provide early itch symptom relief in the atopic dermatitis." (PMID 38541674, 2024). "With an initial diagnosis of atopic dermatitis, upadacitinib (a JAK1 inhibitor) treatment at 15 mg daily was initiated." (PMID 38473222, 2024). "We present the case of an 81-year-old patient with severe atopic dermatitis on upadacitinib, a selective JAK1 inhibitor, who developed HZ and VTE, requiring hospitalization." (PMID 39507180, 2024). "Abrocitinib, an oral small-molecule Janus kinase 1 inhibitor, has been authorized for the treatment of severe atopic dermatitis (AD) and can also provide rapid relief from pruritus." (PMID 39611144, 2024).
atopic dermatitis (continued). "Dr. Kim discussed the molecular and neural mechanisms of chronic itch, in particular, how Janus kinase 1 (Jak1) and several interleukins play a role in atopic dermatitis and other skin itch conditions." (PMID 37794457, 2023). "For the treatment of moderate-to-severe atopic dermatitis in children and adolescents, the monoclonal antibody dupilumab and the selective JAK-1 inhibitor upadacitinib are two modern systemic therapies approved for long-term treatment." (PMID 36769820, 2023). "Abrocitinib is a JAK1 selective inhibitor recently approved for the treatment of moderate-to-severe atopic dermatitis in adults." (PMID 36839707, 2023). "Upadacitinib is a JAK1 inhibitor that has a good safety and efficacy profile and is increasingly being prescribed for atopic dermatitis." (PMID 37077807, 2023). "Since 2021, the selective JAK-1 inhibitor upadacitinib has been approved by the European Medicines Agency (EMA) for the treatment of atopic dermatitis in adolescents aged 12 years and older." (PMID 36769820, 2023). "Ruxolitinib, a JAK inhibitor, has been identified by the FDA as a clinical treatment for Polycythemia, myelofibrosis, chronic graft-versus-host disease (cGVHD), and Atopic dermatitis by targeting JAK1 and JAK2." (PMID 36911202, 2023). "Oclacitinib is a selective inhibitor of Janus kinase 1, licensed for the treatment of clinical signs of canine atopic dermatitis and allergic pruritus in dogs." (PMID 37835664, 2023). "This study aims to explore the mechanism of interleukin-32 (IL-32) affecting atopic dermatitis (AD) through the Janus-activated kinase-1 (JAK1)/microRNA-155 (miR-155) axis." (PMID 35545774, 2022). "The results of these trials are supporting the potential important role of JAK1 inhibition in patients who need fast relief of pruritus and skin inflammation in atopic dermatitis." (PMID 36569854, 2022). "The JAK1 inhibitor abrocitinib, which reduces IL-4 and IL-13 signaling, is being investigated for the treatment of atopic dermatitis." (PMID 34680614, 2021). "In light of these data, we extended our analyses to atopic dermatitis, a second, common, chronic inflammatory skin disease, by examining IL-19 levels in patients enrolled in a phase 2 study for the JAK1/2 inhibitor baricitinib." (PMID 30914699, 2019). "In addition, ruxolitinib, a topical JAK1/2 inhibitor, is Food and Drug Administration–approved for treatment of atopic dermatitis." (PMID 40948688, 2025). "Upadacitinib, an oral, selective Janus kinase 1 inhibitor, approved for use in moderate-to-severe atopic dermatitis as well as psoriatic arthritis may have a potential role in psoriasis treatment." (PMID 39906475, 2025). "JAK inhibitors such as upadacitinib (selective JAK1 inhibitor), abrocitinib (preferred JAK1 inhibitor), and baricitinib (A JAK1/2 inhibitor) have been proven to rapidly alleviate itching and skin lesions in atopic dermatitis, and surpassing conventional immunosuppressants." (PMID 40717900, 2025). "Upadacitinib, an oral JAK1 inhibitor, is Food and Drug Administration–approved in treating various inflammatory conditions including rheumatoid arthritis, ulcerative colitis, and atopic dermatitis." (PMID 40948688, 2025). "Janus kinase (JAK)-1 inhibitors have been approved for moderate-to-severe atopic dermatitis (AD)." (PMID 41255603, 2025). "In Japan, the most recent guidance for the use of oral JAKi in the treatment of AD recommended abrocitinib based on the JAK1 Atopic Dermatitis Efficacy and Safety (JADE) COMPARE (NCT037204700), JADE TEEN (NCT03796676), and JADE Mono‐2 (NCT03575871) trial results." (PMID 38650307, 2024). "Abrocitinib is an oral JAK1 inhibitor currently available for moderate-to-severe atopic dermatitis." (PMID 38203533, 2023). "Oclacitinib is another inhibitor that targets JAK1 and is used to treat Canine allergic dermatitis." (PMID 36911202, 2023).